MYD88 (MYD88 innate immune signal transduction adaptor)
Diseases named in the same sentence as MYD88 in open-access papers (continued):
Sharing a sentence is not in itself a finding about the gene and the disease.
Obesity (continued). "TLR/MyD88 is a classic signaling inflammatory response that also involves in obesity development and is inhibited by the overexpression of PPARγ via the negative control of the expression of TLR4, and then activates the expression of CD36 for promoting fatty acid uptake and fat accumulation." (PMID 40045630, 2025). "The upregulation of siglec-E affects NF-κB responses in a MyD88-dependent manner, suggesting that its regulation of adipogenesis and obesity may occur via the NF-κB signaling pathway." (PMID 39967660, 2025). "Therefore, these compounds provided the material basis for ECT‐mediated regulation of obesity through the TLR4/MyD88/NF‐κB signaling pathway." (PMID 40772014, 2025). "In summary, this study demonstrated that G-SDF and SDFfbs effectively mitigate the double damage caused by obesity and antibiotic exposure by modulating the LPS/TLR4/MyD88/NF-κB pathway, protecting the intestinal barrier, and restoring the gut microbiota balance." (PMID 40659561, 2025). "In our study, we found ECT could regulate obesity via the LPS‐TLR4/MyD88/NF‐κB signaling pathway via RT‐qPCR and Elisa experiments." (PMID 40772014, 2025). "Complete deletion of MyD88 in HFD-fed mice resulted in obesity, IR, and hepatic steatosis." (PMID 38291436, 2024). "In contrast, activation of the TLR4/MyD88 signaling pathway enhances CaMK II activity, thereby facilitating LV remodeling in the setting of chronic pressure overload or obesity to some extent, illustrated that TLR4/MyD88/CaMK II pathway mediated inflammation involved hypertrophic remodeling." (PMID 33324685, 2020). "Therefore, these evidences and current findings together suggest that MyD88 signaling in astrocytes is important in leptin resistance caused by HFD-induced inflammation and obesity pathogenesis." (PMID 32560726, 2020). "Furthermore, our former work demonstrated that TLR4/MyD88/CaMKII signaling pathway contributed to obesity-induced ventricular electrical remodeling." (PMID 32733242, 2020). "In this study, we examined whether MyD88 signaling in hypothalamic astrocytes controls reactive gliosis and inflammatory responses, thereby contributing to the pathogenesis of obesity." (PMID 32560726, 2020). "In the present investigation, we found that GSTO1-1 deficient mice consuming a high fat diet present a similar phenotype to that of TLR4 and MyD88 deficient mice and do not exhibit marked obesity and insulin resistance." (PMID 29259211, 2017). "Therefore, we investigated the cell types in which MyD88 is necessary for the development of obesity-induced inflammation and IR." (PMID 28614714, 2017). "TLR4 and MyD88 play prominent roles in signaling that supports low level inflammation in obesity." (PMID 29259211, 2017). "This suggests that the global MyD88 signaling contributes to regulating the immune response in obesity, but may have differential roles in a tissue-dependent manner." (PMID 28614714, 2017). "Furthermore, Dectin-1 levels in the CD11c+ AT macrophages were increased in the lean and obese MyD88 KO mice, while the Dectin-1 KO mice were protected from obesity and IR." (PMID 28614714, 2017). "In a model of diet-induced obesity, MyD88 KO mice exhibited increased anti-inflammatory endocannabinoids, antimicrobial peptide production, and intestinal regulatory T cells, and were partially protected against diet-induced obesity, diabetes, and inflammation." (PMID 28880224, 2017). "The bacterial flora is altered in obesity and it has recently emerged that Myeloid differentiation primary response gene 88 (MyD88) the adaptor molecule central to all Toll-like receptors (TLRs) is crucial in initiating immune responses to altered bacterial flora." (PMID 27992443, 2016). "The positive correlation between increased IRAK-1 gene expression and these markers in obesity indicates the concordance of the activation of TLR/IL-1R/MyD88 pathway and macrophage recruitment or colonization in the adipose tissue to induce or sustain inflammation." (PMID 26312071, 2015).
Obesity (continued). "We also demonstrate that intestinal epithelial MyD88 deletion increases anti-inflammatory endocannabinoids, restores antimicrobial peptides production and increases intestinal regulatory T cells during diet-induced obesity." (PMID 25476696, 2014). "Recent studies suggest an involvement of MYD88 in HFD-induced obesity and inflammation." (PMID 25546437, 2014). "Thus, intestinal epithelial MyD88 acts as a metabolic sensor that switches host metabolism during diet-induced obesity via mechanisms involving the gut microbiota." (PMID 25476696, 2014). "Targeting MyD88 after the onset of obesity reduces fat mass and inflammation." (PMID 25476696, 2014). "Thus, we show that targeting intestinal epithelial MyD88 is a putative therapeutic target for obesity and related disorders." (PMID 25476696, 2014). "Our work thus identifies intestinal epithelial MyD88 as a sensor changing host metabolism according to the nutritional status and we show that targeting intestinal epithelial MyD88 constitutes a putative therapeutic target for obesity and related disorders." (PMID 25476696, 2014). "MyD88 KO mice are protected from the development of type I diabetes and neuronal MyD88 dependent signaling is involved in the diet-induced leptin and insulin resistance and obesity." (PMID 23305364, 2012). "This suggests that ECT may modulate simple obesity through the TLR4/MyD88/NF‐κB signaling pathway." (PMID 40772014, 2025). "However, deletion of MyD88 in intestinal epithelial cells protects from obesity in high-fat diet fed animals, with improved glucose homeostasis, and reduced hepatic steatosis, fat mass and inflammation, along with an obesity-preventing transferable gut microbiota." (PMID 35237264, 2022). "In line with previous reports, this result might indicate that astrocyte-specific Myd88 KO decreased HFD-induced expression of cytokines in astrocytes, which further indicates crosstalk between astrocytes and microglia and the importance of astrocyte MyD88 signaling in HFD-induced obesity." (PMID 32560726, 2020). "Perhaps not surprisingly given this complexity, our hypothesis that ES-62 might counter HCD-accelerated ageing by virtue of its potential to suppress the chronic MyD88-driven inflammation promoting metabolic deregulation, obesity and ageing, per se proved to be rather simplistic." (PMID 32163524, 2020). "Thus, obese CD11c-MyD88 KO mice are a model of defective T cell activation without measurable alterations in systemic immune cell numbers and cytokines associated with obesity." (PMID 26317499, 2015). "However, it remains unclear how the expression of IRAK-1 adapter protein, which is a critical component of the TLR/IL-1R/MyD88 pathway, is modulated in obesity or T2D." (PMID 26312071, 2015). "Thus, whether such alterations in the IEC MyD88 pathway occur in human intestine and thereby contribute to the onset of obesity and related disorders via gut microbiota-dependent mechanisms requires further investigations." (PMID 25476696, 2014). "A study on the relationship between obesity and arthritis revealed that saturated fatty acids activate TLR4, which initiates the recruitment of MyD88." (PMID 40636390, 2025). "Experimental studies have demonstrated that CNS-specific disruption of myeloid differentiation primary response 88 (MyD88), a critical adaptor for TLR-mediated NF-κB activation, protects mice from leptin resistance and diet-induced obesity." (PMID 41463063, 2025). "COVID-19, Irisin, Exercise, Sedentarism/Aging, and Obesity influence related inflammatory pathways: TLR4, MyD88, MAPK, AMPK, NF-kB, and cytokine production." (PMID 35784579, 2022). "In conclusion, our data show that the AT SRA1 expression correlates with TLRs-3,4,7,9, MyD88, NF-κB, and IRF5 expression in individuals with T2D and with TLR2, IRAK1, and IRF3 expression in individuals with obesity." (PMID 36552771, 2022).
Obesity (continued). "Consistent with our finding of an increased expression of the mentioned markers, similar changes in the AT expression of MyD88, IRAK1, and IRF5 have been reported in individuals with obesity and/or type-2 diabetes." (PMID 36139454, 2022). "When mimicking obesity in a mouse model, deletion of MD1 aggravated high-fat diet-fed induced maladaptive left ventricular hypertrophy via TLR4/MyD88/CaMKII and TLR4/NF-kB signaling." (PMID 35237675, 2022). "Consistent with our finding of the increased expression of these markers, at least in part, similar changes in the adipose tissue expression of MyD88, IRF3, NF-κB, and AML1 have been reported in obesity and/or T2D." (PMID 32188105, 2020). "In the present study, we found that Myd88 expression in hypothalamic astrocytes was increased by long-term HFD feeding and that astrocyte-specific ablation of Myd88 ameliorated the obesity-related metabolic phenotype induced by HFD consumption." (PMID 32560726, 2020). "Our data show strong positive correlations between adipose IRF5 gene expression and that of TLR2, TLR7, TLR8, TLR9, MyD88, IRAK-1, and IRF3 in obesity." (PMID 31718015, 2019). "Our proteomics analysis showed a positive interaction between ANXA and vimentin in the AT of the WT and MyD88 KO DIO mice, suggesting that vimentin is increased during obesity due to low oxygen availability in the AT." (PMID 28614714, 2017). "Saturated fatty acids, which are elevated in obesity, are able to bind and activate toll-like receptor 4 (TLR4) and inhibition of TLR4 or neuronal deletion of the TLR adaptor molecule MyD88 protects from HFD-induced leptin resistance and obesity." (PMID 28270795, 2017). "Thus, we may not exclude the possibility that IEC MyD88 deletion partially protects against diet-induced obesity through mechanisms associated with metabolic functionalities assumed by gut microbes." (PMID 25476696, 2014). "Previously, it has been shown an increase in protein expression of TLR-2, MyD88, and TRAF6 as well as NF-κB in human adipose tissue in states of obesity and diabetes mellitus type 2." (PMID 21266050, 2011). "Dectin-1 activation exacerbates obesity and insulin resistance under a high-fat diet in mice lacking MyD88, a proximal adaptor of most TLRs." (PMID 35237264, 2022). "Mice deficient in Myd88, but not for TRIF, are protected from diet-induced obesity, suggesting that obesity and insulin resistance are controlled by different mechanisms." (PMID 30931309, 2019). "Surprisingly, we did not detect any major effect of injury and obesity on the expression levels of TNF or the associated genes Bcl3, Errfi1, Irak3, Myd88, and Thbs1 in our obese model." (PMID 29922174, 2018). "This contrasts the phenotype of our and other reports of the global MyD88 KO mice and contrasts the findings indicating that depletion of MyD88 in myeloid cells does not protect mice from obesity-induced IR." (PMID 28614714, 2017). "Together, our data indicate that Dectin-1 regulates AT inflammation by promoting CD11c+ AT macrophages in the absence of MyD88 and identify a role for Dectin-1 in chronic inflammatory states, such as obesity." (PMID 28614714, 2017). "The data show that MyD88 in VAT cells with dendritic- or macrophage-like properties is crucial for T cell activation ex vivo and for the dramatic rise in T and B cells in VAT in the setting of obesity." (PMID 26317499, 2015). "An ip administration of leptin (2 mg/kg body weight) effectively reduced food intake and body weight in both control and Myd88ΔGFAP mice fed a STD diet, indicating that astrocyte-specific Myd88 KO did not affect leptin responsiveness under non-obesity conditions." (PMID 32560726, 2020). "Furthermore, mice lacking the TLR adaptor molecule myeloid differentiation primary response 88 (MyD88) were protected against diet-induced obesity." (PMID 30626117, 2019). "Next, we investigated whether the absence of MyD88 would affect the obesity-induced AT inflammation." (PMID 28614714, 2017).
Obesity (continued). "We observed that depletion of MyD88 in adipocytes does not protect mice from obesity and IR." (PMID 28614714, 2017). "However, how MyD88 contributes to obesity-induced IR and its actions in specific tissues are still not completely understood." (PMID 28614714, 2017). "The correlations of IRAK-1 gene expression were assessed against clinical markers of obesity, local proinflammatory mediators, monocyte/macrophage markers, systemic inflammatory markers, and more importantly, against upstream signaling components of the TLR/IL-1R/MyD88 pathway." (PMID 26312071, 2015). "The data thus far have established the CD11c-MyD88 KO DIO mouse as a model to investigate the role of endogenously activated T and B cells in obesity-associated insulin resistance, because neither immune cell numbers in the periphery nor VAT myeloid-derived cells and their cytokines are affected." (PMID 26317499, 2015). "An interesting finding from our study is that deletion of MyD88 in CD11c+ cells does not affect VAT inflammation aside from the expected decrease in T cell cytokines, which suggests that CD11c+ cell-mediated VAT inflammation in obesity is MyD88-independent." (PMID 26317499, 2015).
diffuse large B-cell lymphoma (77 papers, 2013 to 2025). "MYD88-L265P encoding mutations occur in diffuse large B-cell lymphomas, in lymphoplasmacytic lymphomas and in few marginal zone lymphomas (MZL)." (PMID 36675328, 2023). "Activating MYD88 mutations are found in 10–20% of activated B-cell-like diffuse large B-cell lymphoma (ABC-DLBCL) cases, but are rare in germinal center-like DLBCL (GCB-DLBCL) and most other B cell non-Hodgkin lymphomas." (PMID 37591861, 2023). "Damaging mutations in primary cutaneous diffuse large B-cell lymphoma of the leg type, involving MYD88 gene, or BCL6 and MYC translocations or CDKN2A deletions are useful for diagnostic purposes." (PMID 36291756, 2022). "A subset of diffuse large B cell lymphoma patients carry the MyD88 L265P mutation, associated with overactivation of the TLR7/9/MyD88 pathway." (PMID 36479129, 2022). "Primary cutaneous diffuse large B-cell lymphoma of the leg type involves characteristic mutations in the MYD88 gene or CDKN2A deletions." (PMID 36291756, 2022). "69% of patients with cutaneous diffuse large B cell lymphoma (CBCL) carry MyD88 L265P mutation, which is significantly associated with shorter disease-specific survival." (PMID 35309296, 2022). "Hck activation can be triggered by IL‐6 in MYD88‐mutated Waldenström macroglobulinemia and diffuse large B‐cell lymphoma." (PMID 34482626, 2022). "Somatic mutations in MyD88 have also been found which contribute to human malignancies for both chronic lymphocytic leukaemia and more commonly diffuse large B cell lymphoma." (PMID 30583727, 2018). "Good clinical responses have been reported for a small subset of patients with diffuse large B-cell lymphoma carrying MyD88 mutations." (PMID 29153976, 2017). "The precise clinicopathologic significance of myeloid differentiation primary response gene (MYD88) L265P mutation in diffuse large B-cell lymphomas (DLBCLs) remains elusive." (PMID 28496180, 2017). "MyD88 (L265P) is highly recurrent, with 29% of a cohort of 382 patients with activated B-cell-like diffuse large B-cell lymphoma possessing this mutation." (PMID 27733853, 2016). "ND-2158 and ND-2110 inhibited IRAK4 and NF-κB activity in activated B cell–like (ABC) subtype of diffuse large B cell lymphoma (DLBCL) cell lines with L265P mutation in MyD88." (PMID 27845762, 2016). "Gain-of-function mutations in the TLR adaptor protein MYD88 found in 39% of the activated B cell type of diffuse large B cell lymphomas and almost 100% of Waldenström’s macroglobulinemia further highlight the involvement of TLRs in these malignancies." (PMID 25132836, 2014). "For example, a subset (29%) of activated B-cell type diffuse large B-cell lymphomas (ABC DLBCL) with a very aggressive phenotype were recently found to carry an oncogenic MyD88 mutation (L265P) that promotes survival." (PMID 25452754, 2014). "Dysregulated and constitutively active MyD88 signaling caused by the mutation L265P within its TIR domain is characteristic for distinct types of diffuse large B-cell lymphoma (e.g., Waldenström’s macroglobulinaemia, WM), where almost 90% of patients harbor L265P mutation." (PMID 35069570, 2021). "Previous findings suggest a therapeutic potential for IRAK4 inhibitors for the activated B-cell-like (ABC) subtype of diffuse large B-cell lymphoma (DLBCL) presenting with MYD88 mutations, as well as for autoimmune disorders and other malignancies that depend on TLR signaling." (PMID 31197259, 2020). "MYD88 mutations have been reported to be pathogenetically relevant in some cutaneous diffuse large B-cell lymphomas, leg type, and curiously seem to be mutually exclusive from other cancer-promoting mutations that activate the NF-κB pathway including BRAF, PIK3, or STAT3." (PMID 33333886, 2020). "Diffuse large B-cell lymphoma (DLBCL) is a heterogeneous disease, with MYD88 mutations associated with poor outcomes." (PMID 40616640, 2025).